MC1R (melanocortin 1 receptor)
Diseases named in the same sentence as MC1R in open-access papers (continued):
Sharing a sentence is not in itself a finding about the gene and the disease.
melanoma (continued). "Since MC1R is known to be overexpressed on the surface of cancer cells in a subset of melanoma patients, we determined melanoma cell lines with a high expression of MC1R." (PMID 38256168, 2024). "Thus, since the dark phenotype largely depends on the capacity to respond to stimulation of the pro-melanogenic peptide α-MSH and consequently on the MC1R sequence, an unexpectedly increased melanoma risk could be hypothesized for individuals bearing the wild-type form of this receptor." (PMID 38474338, 2024). "It was also concluded that uveal melanoma OCM-1 is a good human melanoma experimental model because of its high MC1R expression and fairly good growing capability in comparison with other human melanoma models." (PMID 38256168, 2024). "Stepwise elevation of MC1R expression has been noted in different stages of melanoma progression (nevi, primary, metastasis)." (PMID 39171057, 2024). "Subsequently, the over-expressions of MC1R and αvβ3 integrin receptor on melanoma led to the development of radiolabeled RGD-conjugated α-MSH hybrid peptides as dual-receptor-targeting imaging probes for melanoma imaging." (PMID 38708130, 2024). "The presence of α-MSH receptors (MC1R) on both murine and human melanoma cells suggests that α-MSH analogs can be developed into targeted melanoma imaging or therapeutic agents." (PMID 38256168, 2024). "Data from a B16F10 mouse melanoma model suggest that increased activity of MC1R as result of UVR exposure dampens the anti-tumor T-cell response." (PMID 38672543, 2024). "To test this possibility, we used A375 human melanoma cell line, which contains an arginine-to-cysteine RHC variant at the residue 151 (R151C) of MC1R conferring its attenuated function." (PMID 39621784, 2024). "The overexpression of MC1R on malignant melanomas suggests that peptides such as α-MSH (Ac-Ser-Tyr-Ser-Met-Glu-His-Phe-Arg-Trp-Gly-Lys-Pro-Val-NH2, an N-terminal acetylated and C-terminal amidated tridecapeptide) regulate skin pigmentation in most vertebrates." (PMID 38256168, 2024). "This is contrary to the previous belief of most researchers that the overexpression of MC1R in early melanoma cells will promote its proliferation." (PMID 39228912, 2024). "Miao and colleagues developed another class of MC1R-targeted peptide radiopharmaceutical, GGNle-CycMSHhex, for melanoma imaging and therapy." (PMID 38708130, 2024). "Presumably, higher MC1R density and stronger αvβ3 integrin receptor binding affinity would further enhance the success of dual-receptor-targeted radiolabeled peptides for melanoma detection." (PMID 38708130, 2024). "Among the genes we identified, many are known melanoma susceptibility genes including CASP8, ARNT, and OCA2 (downregulated), PARP1, SETDB1, MTAP, SLC45A2, and MC1R (upregulated), and MX2 (both up‐ and downregulated)." (PMID 38308491, 2024). "The development of melanoma is largely influenced by the signaling of the melanocortin one receptor (MC1R), which plays an essential role in the synthesis of melanin in the skin." (PMID 38534742, 2024). "In summary, in light of recent approaches to target MC1R in melanoma, we demonstrate that MC1R expression is significantly higher in melanomas than nevi, making MC1R a target worthy further evaluation in radiopharmaceutical trials." (PMID 37790306, 2023). "While the normal expression of MC1R protein is low, melanocytes express approximately 700 protein units, with slightly higher amounts found on melanoma cells." (PMID 37569558, 2023). "Taken together, these results demonstrates that the repression of Cxcl9/10 expression by MC1R is critical for B16F10 melanoma to evade immunosurveillance." (PMID 37714844, 2023). "Due to its critical roles in enhancing DNA repair, mutations of the melanocortin-1 receptor (MC1R), a GPCR, have been correlated to a higher risk of melanoma." (PMID 37759431, 2023).
melanoma (continued). "MC1R-targeting agents are being investigated in clinical trials in melanoma patients, yet large studies investigating the rate and degree of MC1R expression in primary and metastatic human melanoma tissue are lacking." (PMID 37790306, 2023). "In the metastatic melanoma cohort, MC1R expression and mucosal melanomas were independent predictors of inferior overall survival." (PMID 37790306, 2023). "MC1R is an important melanoma-specific target that has been proposed for molecular imaging applications." (PMID 36674595, 2023). "Additional studies are warranted to determine its functional significance in melanoma progression and its utility as a predictive biomarker in patients receiving MC1R-directed therapies." (PMID 37790306, 2023). "One such characteristic is the overexpression of the MC1R cell surface endocytic receptor on the surface of human melanomas, which makes it a crucial tumor marker." (PMID 37569558, 2023). "In the metastatic melanoma cohort, MC1R expression (HR 1.7, p = 0.021) and mucosal vs. primary melanoma (HR 2.4, p = 0.011) were independent predictors of inferior overall survival." (PMID 37790306, 2023). "In human melanomas, high MC1R expression correlates with reduced CXCL9/10/11 expression, impaired T cell infiltration, and poor patient prognosis." (PMID 37714844, 2023). "Studies have revealed that the MC1R signaling pathway is crucial in treating melanoma, as it affects various physiological changes in melanocytes." (PMID 37569558, 2023). "Our study implicates MC1R as a melanoma immunotherapy target and suggests GNAS-PKA signaling as a pan-cancer oncogenic pathway inhibiting antitumor T cell response." (PMID 37714844, 2023). "Together with our results, it is plausible that melanoma cells with high MC1R expression can take advantage of elevated circulating α-MSH to activate MC1R signaling to dampen antitumor T cell response." (PMID 37714844, 2023). "α-MSH/MC1R/cAMP axis converges to the regulation of MiTF expression with a pivotal role for homeostasis but when impaired in melanoma environment it takes a role in tumor progression and survival." (PMID 37608347, 2023). "As for MC1R- and PTEN-mutated patients, a pigmented reticular pattern was the main dermoscopic feature, with an atypical network characterizing malignant melanoma (SSM, Breslow 0.8 mm)." (PMID 37568588, 2023). "Thus, WT MC1R may promote genomic stability by (i) activating eumelanogenesis to shield nuclei from UVR, (ii) lowering oxidative stress, and (iii) triggering a DNA damage response, which is consistent with the lower mutation load in MC1R-WT compared with MC1R-variant melanomas." (PMID 37762683, 2023). "We show a stepwise elevation of MC1R expression in different stages of melanoma progression (nevi, primary, metastasis)." (PMID 37790306, 2023). "First of all, 67Cu-NOTA-PEG2Nle-CycMSHhex displayed higher MC1R-specific cellular uptake than 67Cu-NOTA-GGNle-CycMSHhex on B16/F10 melanoma cells." (PMID 37345092, 2023). "Another class of MC1-R targeting agents extensively used to detect melanomas or evaluate the cellular levels of MCR1 are the NAPamide analogs." (PMID 36674595, 2023). "Melanocortin 1 receptor (MC1R) and microphthalmia-associated transcription factor (MITF) are considered moderate-penetrance melanoma genes." (PMID 37958811, 2023). "A concern arises regarding the possible stimulation of abnormal melanocytes in the human body, given that melanoma tumors comprise a mixture of cells with only a subset expressing MC1R." (PMID 38256864, 2023). "In this work, we perform pooled in vivo CRISPR knockout screening using the mouse B16F10 melanoma model and discover that depletion of melanocortin-1 receptor (MC1R) in melanoma cells activates antitumor T cell response." (PMID 37714844, 2023).
melanoma (continued). "To investigate the molecular mechanisms by which MC1R promotes melanoma immune evasion, we performed RNA-seq to compare the transcriptomes of B16F10-dCas9 cells transduced with the Mc1r sgRNA versus the NTC sgRNA in the absence or presence of α-MSH." (PMID 37714844, 2023). "Preclinical studies have investigated the use of radiolabeled alpha-melanocyte-stimulating hormone (α-MSH), a natural ligand of MC1R, for targeted radionuclide therapy of melanoma." (PMID 39380959, 2023). "The human MC1R is primarily found on melanocytes and malignant melanoma cells and consists of 317 amino acids." (PMID 37569558, 2023). "In our cohort, out of 115 patients referred to genetic counseling for melanoma, 25 tested positive (21.7%) for critical mutations: CDKN2A (n = 12), MITF (n = 3), BAP1 (n = 1), MC1R (n = 3), PTEN (n = 1), TYR (n = 2), OCA2 (n = 1), and SLC45A2 (n = 2)." (PMID 37568588, 2023). "Together, these results highlighted a central role of MC1R palmitoylation in protection against melanoma." (PMID 37759431, 2023). "MC1R has been identified as a potential target for radionuclide therapy in melanoma, as its expression is highly upregulated in melanoma cells compared to normal skin cells." (PMID 39380959, 2023). "The favorable tumor targeting and biodistribution properties of 67Cu-NOTA-PEG2Nle-CycMSHhex underscored its potential as an MC1R-targeted therapeutic peptide for melanoma treatment." (PMID 37345092, 2023). "Our study reveals a distinct function of MC1R in promoting the escape of a subset of melanomas with melanocytic features from immune surveillance." (PMID 37714844, 2023). "Starting from this background, in this study, we characterized the role of PI3K in glucose metabolism rearrangement induced by αMSH-mediated MC1R stimulation in melanoma cell lines." (PMID 37048170, 2023). "NCT04904120 aims to evaluate the safety and feasibility of using the agents (203Pb-VMT01 and 68Ga-VMT02) to image melanoma tumors expressing the melanocortin sub-type 1 receptor (MC1R)." (PMID 39380959, 2023). "Over the past years, we have developed a new class of MC1R-targeted peptide radiopharmaceuticals that include the core structure of Gly-Gly-Nle-c[Asp-His-DPhe-Arg-Trp-Lys]-CONH2 (GGNle-CycMSHhex) for melanoma imaging and therapy." (PMID 37345092, 2023). "We observed that MC1R-high melanomas were more likely to be low in T-cell infiltration and effector functions in comparison to MC1R-low melanomas." (PMID 37714844, 2023). "Taken together, these observations indicate that depletion of MC1R from B16F10 cells enhances the antitumor immune responses against B16F10 melanoma." (PMID 37714844, 2023). "Utilizing this threshold, 90% of nevi, 67% of primary melanomas and 38% of metastases had low MC1R expression levels." (PMID 37790306, 2023). "We tested the requirement of the classical cAMP effector PKA for MC1R-mediated immune evasion of B16F10 melanoma." (PMID 37714844, 2023). "The drug-MT-II conjugates efficiently bound to MC1R and selectively delivered drugs to A375 melanoma cells in vitro." (PMID 37569558, 2023). "Previous studies proved that radiolabeled α-MSH analogue NAPamide (Ac-Nle-Asp-His-D-Phe-Arg-Trp-Gly-Lys) derivatives serve as effective molecular probes for the determination of the MC1-R expression pattern of the melanoma cells." (PMID 37765089, 2023). "We offer insight into the distribution of MC1R in melanoma progression and delineated a stepwise escalation in MC1R expression during progressive stages of melanoma, transitioning from benign nevi to primary melanoma to metastatic melanoma." (PMID 37790306, 2023). "Taken together, we conclude that depletion of MC1R activates antitumor T cell response in B16F10 melanoma." (PMID 37714844, 2023). "We found that one of the peptides, namely 67Cu-NOTA-PEG2Nle-CycMSHhex, exhibited favorable melanoma targeting and biodistribution properties that underscored its potential as an MC1R-targeted therapeutic peptide for melanoma treatment in the future." (PMID 37345092, 2023).
melanoma (continued). "[212Pb]VMT01 is a melanocortin 1 receptor (MC1R) targeted theranostic ligand in clinical development for alpha particle therapy for melanoma." (PMID 36144563, 2022). "We previously reported protective effects of melanoma-related MC1R in nigrostriatal dopaminergic neuron survival under basal conditions and in toxin models of PD." (PMID 35197079, 2022). "In primary human melanocytes, the MC1R knockdown significantly impairs survival and DNA repair in response to UVR, hence increasing the risk of melanoma." (PMID 36551302, 2022). "Activating the palmitoylation modification of the MC1R protein has been demonstrated as a preventive and treatment strategy in redhead melanoma." (PMID 36551302, 2022). "The overexpression or inhibition of MC1R expression enhanced or reduced melanoma migration in mice, respectively." (PMID 35619714, 2022). "MC1R generates derived peptides during the expression of melanoma cells to induce a cytotoxic T lymphocyte (CTL) response." (PMID 36551302, 2022). "MC1-R is thought to play a role in melanoma progression through the activation of MET, a proto-oncogene and key regulator of metastasis in many cancers." (PMID 36499015, 2022). "MC1R is overexpressed on the cell surface of most human melanomas making MC1R a valuable marker of these tumors." (PMID 35452484, 2022). "The αMSH/MC1R agonism has a role of prevention of skin cancer including melanoma by up regulating two important photo‐protective mechanisms, DNA repair and pigmentation." (PMID 35665216, 2022). "In vitro studies using melanoma cells, which express MC1R, indicates that αSyn is highly expressed and promotes melanoma cell survival." (PMID 35197079, 2022). "Melanoma is a highly malignant tumor derived from melanocytes, which differentiate via melanogenesis regulated by melanocortin 1 receptor (MC1R), tyrosinase (TYR), TYR-related protein-1 (TYRP1), and dopachrome tautomerase (DCT)." (PMID 35619714, 2022). "Positron emission tomography (PET) imaging of an MC1R-targeted peptide 68Ga-DOTA-GGNle-CycNSHhex in melanoma patients has established clinical proof-of-concept of MC1R as a target for imaging and therapy." (PMID 36144563, 2022). "For melanoma treatment, targeted treatment can be achieved by labeling small molecules, such as melanin ligands, peptides that recognize a specific receptor (MC1R), or antibodies (anti-melanin, anti-GD3)." (PMID 35158973, 2022). "The high MC1R expression not only represents a molecular characteristic of melanoma, but also has important implications for tumor cell division and metastasis." (PMID 35401191, 2022). "The MC1R-mediated cAMP signaling has been identified as a major mechanism in regulating pigmentation, adaptive tanning, and melanoma resistance." (PMID 35140838, 2022). "CSPG4 and MC1R are surface antigens often expressed on melanoma cells, and they participate in many biological behaviors of melanoma." (PMID 35401191, 2022). "MC1R is melanocortin 1 receptor gene directly connected with activation of cell division and metastasis in malignant melanoma." (PMID 35795065, 2022). "MC1-R, a protein used to identify fusion events in melanoma, was found in CTCs and CTM and shows promise as a prognostic marker in ovarian cancer." (PMID 36499015, 2022). "In particular, the association of MC1R RHC variant alleles D84E, R142H, R151C, R160W and D294H with a direct effect on melanoma risk has been confirmed by several studies and meta-analyses." (PMID 34356109, 2021). "Several genetic interactions of MC1R in melanoma also include ASIP and X-ray repair cross-complementing protein (XRCC)." (PMID 34356109, 2021). "Melanocortin 1 receptor (MC1R) has long been investigated as a promising target for metastatic melanoma drug delivery due to its overexpression in melanoma cells and relatively low expression in normal cells." (PMID 34359580, 2021).
melanoma (continued). "MC1R variants, especially the RHC one, are known to modulate the color and the dermoscopic pattern of melanomas and nevi, resulting in hypopigmentation and the presence of fewer dermoscopic structures, which highlight the vascular pattern of these tumors." (PMID 34442055, 2021). "Pigmentation and melanocyte differentiation related mutations in MC1R (melanocortin 1 receptor) and MITF (microphthalmia associated transcription factor) have also been found in melanoma." (PMID 35127523, 2021). "MC1R R carriers develop melanomas with reduced dermoscopic structures, lower total dermoscopy score, lower prevalence of atypical pigment network, and less blotch of pigment." (PMID 34440462, 2021). "One particularly attractive avenue for this drug-targeting paradigm has been the use of radiolabeled synthetic peptide analogs of α-melanocyte stimulating hormone (α-MSH) to deliver radionuclides to the melanoma tumor microenvironment via binding with MC1R." (PMID 34359580, 2021). "Radiolabeled synthetic α-MSH analog VMT01 was employed to deliver Pb isotopes 203Pb and 212Pb to melanoma cells via binding with MC1R." (PMID 34359580, 2021). "The correlation between MC1R and melanoma has been studied extensively, but the value of MC1R in the prognosis or therapeutic potential of CRC has been investigated to a lesser extent." (PMID 34698109, 2021). "Of note, genetic variants of the melanocortin 1 receptor MC1R are linked to high-risk phenotypic alterations in pigmentation—such as fairer skin, hair, and eye colors—that confer a predisposition to melanoma." (PMID 34638397, 2021). "Given the similarity of pathways involved in melanoma and RCC biology, a possible role of MC1R variants in renal cell physiology and RCC deserves additional investigations." (PMID 34067022, 2021). "Abnormal expression of MC1R is associated with the development of skin cancer, and it has been reported that high expression of MC1R in melanoma promotes the progression of its development." (PMID 34698109, 2021). "In this study, we demonstrated the feasibility of delivering alpha-particle radiation to murine melanoma tumors using a 212Pb radiolabeled peptide [212Pb]VMT01 that targets the melanocortin 1 receptor (MC1R)." (PMID 34359580, 2021). "The MC1R variants associated with the red hair color phenotype (RHC) are commonly classified as R alleles and are the most-involved SNPs in melanoma susceptibility." (PMID 34356093, 2021). "Melanocortin 1 receptor (MC1R) is thought to be a marker of poor prognosis and a potential target for the treatment of melanoma." (PMID 34698109, 2021). "This CGI has been shown to control MC1R expression, with a slight trend of increased methylation in melanomas showing homozygous RHC MC1R, as compared to WT and heterozygous tumors." (PMID 34356109, 2021). "The melanocortin 1 receptor (MC1R) regulates pigmentation, adaptive tanning, and melanoma resistance by activating adenylyl cyclase which accumulates intracellular cyclic AMP (cAMP) levels." (PMID 34064641, 2021). "For example, several variants in MC1R, as well as MITF p.Glu318Lys, act as low/moderate risk variants for melanoma." (PMID 34262154, 2021). "Other POMC-derived peptides, such as α-MSH and melanocortin 1 receptor (MC1R) are also expressed in melanoma cell lines, nodular and metastatic melanoma." (PMID 34068618, 2021). "MITF is known as a central regulator of melanoma cell survival, proliferation, and differentiation, and the factors that regulate it include MC1R, MART-1, SOX10 and PAX3." (PMID 33672928, 2021). "In this study, 212Pb radiolabeled peptide [212Pb]VMT01 targeting MC1R was used to deliver α-particle radiation to melanoma cells." (PMID 34359580, 2021). "In vivo biodistribution of Pb-labeled VMT01 was determined using [203Pb]VMT01 in female athymic nude mice bearing MC1R-positive B16-F10 melanoma." (PMID 34359580, 2021).